CTNND1 (catenin delta 1)
Diseases named in the same sentence as CTNND1 in open-access papers (continued):
Sharing a sentence is not in itself a finding about the gene and the disease.
breast tumors (4 papers, 2007 to 2017). "The same approach finds a significant signature for basal-like breast tumors that distinguishes them from other breast cancer subtypes and which includes the tumor-driver CTNND1." (PMID 25578962, 2015). "In our GSEA analysis, we found that CTNND1 was ubiquitously expressed in all breast tumors and MCF-7 and ZR75-1 cells, which made it hard to discriminate the relation of this gene in the cell lines in the light of breast tumors we examined." (PMID 17883861, 2007). "We applied this method to more than 4000 samples from the The Cancer Genome Atlas project to obtain novel splicing signatures that are predictive for nine different cancer types, and find a specific signature for basal-like breast tumors involving the tumor-driver CTNND1." (PMID 25578962, 2015).
glioblastoma (4 papers, 2019 to 2022). The most malignant astrocytic tumor (WHO grade IV). "We confirmed that SNHG29 regulates miR-223-3p/CTNND1 axis to promote glioblastoma progression via Wnt/β-catenin signaling pathway, implying a potential tactic for the treatment of glioblastoma patients." (PMID 31889897, 2019). "Then, the inhibitory effect of SNHG29 knockdown on the proliferative ability of glioblastoma cells was abolished by transfection pcDNA3.1/CTNND1 into U87 and U251 cells." (PMID 31889897, 2019). "All in all, SNHG29 regulates miR-223-3p/CTNND1 axis to promote glioblastoma progression via Wnt/β-catenin signaling pathway." (PMID 31889897, 2019). "In conclusion, SNHG29 regulates miR-223-3p/CTNND1 axis to promote glioblastoma progression via Wnt/β-catenin signaling pathway, offering a potential therapeutic point for glioblastoma patients." (PMID 31889897, 2019). "Besides, LRRC75A-AS1 has been validated in glioblastoma, and it regulates the miR-223–3p/CTNND1 axis to promote glioblastoma through Wnt/β-catenin pathway." (PMID 32811810, 2020). "Meanwhile, CTNND1 expression was also up-regulated in glioblastoma cells." (PMID 31889897, 2019). "Taken together, CTNND1 served as the downstream target of miR-223-3p in glioblastoma." (PMID 31889897, 2019). "Collectively, SNHG29 promoted glioblastoma progression by regulating CTNND1 expression." (PMID 31889897, 2019). "This research was the first time to investigate the function and mechanism of SNHG29 in glioblastoma and we verified that SNHG29 regulates miR-223-3p/CTNND1 axis to promote glioblastoma progression via Wnt/β-catenin signaling pathway." (PMID 31889897, 2019). "Compared with control, CTNND1 expression was up-regulated in glioblastoma tissues whereas FOXO1 indicated no differential expression." (PMID 31889897, 2019).
liver cancer (4 papers, 2014 to 2024). An epithelial or non-epithelial malignant neoplasm that arises from the liver. "miR-298 directly targets catenin delta 1 (CTNND1), and the low expression of miR-298 may be a powerful assistant for the proliferation and invasion of liver cancer cells." (PMID 38584703, 2024).
metastatic disease (4 papers, 2016 to 2025). "Among these, the CTNND1 (p120 catenin) isoform switch was previously shown to induce tumor cell invasion and to predict metastatic disease via Rho GTPase." (PMID 38069324, 2023). "Our study points to a novel function of CTNND1 in HCC metastasis through promoting two essential characteristics of metastatic disease in HCCs: migration and invasion." (PMID 27193094, 2016). "Our results demonstrate that CTNND1 regulated these essential characteristics of metastatic disease, and that CTNND1-induced processes are reversible with the suppression of CTNND1 expression, thus providing us with a potential therapeutic option to manipulate CTNND1 levels in clinical HCC practice." (PMID 27193094, 2016).
triple-negative breast carcinoma (4 papers, 2017 to 2022). An invasive breast carcinoma which is negative for expression of estrogen receptor (ER), progesterone receptor (PR), and human epidermal growth factor receptor 2 (HER2). "Clinically, patients with triple-negative breast cancer and lower level of CTNND1 had shorter overall survival (OS) and distant metastasis-free survival (DMFS)." (PMID 34830862, 2021). "Here, we report that CTNND1 is downregulated in both primary tumors and metastatic bone lesions of patients with triple-negative breast cancer (TNBC)." (PMID 34830862, 2021). "Thus, CTNND1 may be a novel biomarker for early predicting bone metastasis of triple-negative breast cancer." (PMID 34830862, 2021).
esophageal squamous cell carcinoma (3 papers, 2015 to 2022). Esophageal squamous cell carcinoma (ESCC) is a type of esophageal carcinoma (EC) that can affect any part of the esophagus, but is usually located in the upper or middle third. "While a number of previous studies have already indicated the potential importance of CTNND2/WNT-signaling in EAC, a potentially more striking observation is that deletion of CTNND1 has been shown to lead to esophageal squamous cell carcinoma (ESCC) development." (PMID 35164838, 2022).
Familial exudative vitreoretinopathy (3 papers, 2022 to 2026). Familial exudative vitreoretinopathy (FEVR) is a rare hereditary vitreoretinal disorder characterized by abnormal or incomplete vascularization of the peripheral retina leading to variable clinical manifestations ranging from no effects to minor anomalies, or even retinal detachment with blindness. "Recently, CTNND1 germline variants have been also linked with familial exudative vitreoretinopathy." (PMID 38796558, 2024).
adenocarcinoma of the lung (2 papers, 2016 to 2017). "ZDHHC5 was previously seen involved in neoplasia with different partners: a ZDHHC5-SMTNL1 fusion was found in SCC of the ovary, a CTNND1-ZDHHC5 in adenocarcinoma of the lung, ZDHHC5-LCT in adenocarcinoma of the breast, and MEF2D-ZDHHC5 in grade III-IV astrocytoma of the brain." (PMID 28186972, 2017).
autism (2 papers, 2019 to 2021). Persistent deficits in social interaction and communication and interaction as well as a markedly restricted repertoire of activity and interest as well as repetitive patterns of behavior.
cleft lip (2 papers, 2024 to 2026). Congenital defect in the upper lip where the maxillary prominence fails to merge with the merged medial nasal prominences. "Patients with cleft lip have previously been shown to harbor variants in CDH1, while variants in CTNND1 are among the most common genetic causes of cleft lip in humans." (PMID 41231213, 2026). "A recent study found that CTNND1 was recurrently mutated in a study of 841 orofacial cleft (OFC) cases, making it the most common genetic cause of cleft lip in that population." (PMID 41231213, 2026). "Previous studies indicate that CDH1, CTNND1, and MYH9 gene disruption may contribute to cleft lip in humans." (PMID 41231213, 2026).
cleft palate (2 papers, 2020 to 2023). Cleft palate is a fissure type embryopathy that affects the soft and hard palate to varying degrees. "Due to advances in next-generation sequencing, CTNND1 has been implicated in human diseases including cleft palate and blepharocheilodontic (BCD) syndrome albeit only recently." (PMID 32196547, 2020). "CTNND1 has recently been linked to non-syndromic cleft palate." (PMID 32196547, 2020). "The CTNND1 gene has also been associated with BCD, and the involvement of another cadherin–catenin complex gene in cleft palate and BCD, in addition to its important function in the maintenance and stability of cell adhesion, which makes this gene an ideal candidate for GC predisposition." (PMID 37686589, 2023).
colorectal tumor (2 papers, 2016 to 2020). "Likewise, CTNND1 is known to be required for nuclear translocation of E-cadherin which in turn regulates β-catenin activity, thereby promoting increased expression of downstream genes and accelerating colorectal tumor growth and migration." (PMID 32718059, 2020).
diabetes (2 papers, 2021 to 2025). "After a variety of bioinformatics analyses and real-time PCR detection, PVR and CTNND1 were classified as possible candidates that caused neutrophil migration disorders in diabetes." (PMID 33902006, 2021).
ductal breast carcinoma (2 papers, 2007 to 2025). "Immunodetectable diffuse cytoplasmic localization of CTNND1 is found in lobular carcinoma, whereas ductal breast carcinoma retains the dominant membrane immunostaining pattern." (PMID 17883861, 2007).
behavioral disorders (1 paper, 2020). "Beyond the known phenotypes associated with CTNND1 and CDH1, we note the novel phenotypes seen in our patients, which include the heart anomalies and behavioral disorders." (PMID 32196547, 2020).
bladder cancer (1 paper, 2014). "Some splicing events have been reported to be related to bladder cancer using exon arrays, including CD44, CLSTN1 and CTNND1." (PMID 24622401, 2014).
bone metastasis (1 paper, 2021). Transfer of a neoplasm from its primary site to bones. "Clinically, TNBC patients with lower CTNND1 were associated with a higher rate of bone metastasis and shorter OS, DMFS." (PMID 34830862, 2021). "CTNND1 may be a biomarker to early and accurately predict the risk of the bone metastasis in TNBC patients." (PMID 34830862, 2021).
Burn McKeown syndromes (1 paper, 2020). "Thus, our data implicate CTNND1 variants as causative of a broad-spectrum syndrome that overlaps with DiGeorge VCF syndrome as well as other disorders of craniofacial development such as CHARGE and Burn McKeown syndromes." (PMID 32196547, 2020).
hereditary cancer syndromes (1 paper, 2021). "Among them, APC, FAT4, CTNND1 and TLR2 seem to be the most promising genes because of their role in hereditary cancer syndromes, tumor suppression, cell adhesion and Helicobacter pylori recognition, respectively." (PMID 33525650, 2021).
lymphoma (1 paper, 2023). A malignant (clonal) proliferation of B- lymphocytes or T- lymphocytes which involves the lymph nodes, bone marrow and/or extranodal sites. "CTNND1 may have a genetic variant in Border Collies that has influenced the expression of the gene or increases the risk for lymphoma; however, only two cases shared homozygous haplotypes across the gene." (PMID 37756103, 2023).
metastatic melanoma (1 paper, 2025). A melanoma that has spread from its primary site to another anatomic site. "Beyond E-cadherin, we observed enrichment of proteins that preferentially associate with nonpalmitoylated CTNND1, including filaggrin (FLG), plakophilin-1 (PKP1), and transglutaminase 1 (TGM1), all linked to poor clinical outcomes in metastatic melanoma." (PMID 41321310, 2025).
osteomyelitis (1 paper, 2025). An acute or chronic inflammation of the bone and its structures due to infection with pyogenic bacteria. "In osteomyelitis, disruption of these junctions facilitates bacterial invasion and spread, and reduced CTNND1 expression may therefore compromise structural barriers against Staphylococcus aureus." (PMID 41278027, 2025).
skin inflammatory disease (1 paper, 2024). "Mice deficient in CTNND1 exhibited a skin inflammatory disease, and impaired umbilical cord wound healing has been reported." (PMID 39601342, 2024).
stomach tumors (1 paper, 2016). "It is well recognized that inactivation of E-cadherin leads to cytosolic translocation of CTNND1 in colon, breast, bladder, lung, pancreas, prostate, and stomach tumors, which has been associated with tumor malignancy." (PMID 27193094, 2016).
tumor (92 papers, 2009 to 2026). "For instance, we noticed that the penultimate exon of catenin delta 1 (CTNND1), a tumor suppressor often linked with the development and progression of BC, was more frequently skipped in TNBC than ER+ BC." (PMID 41273175, 2025). "By intersecting anoikis-related genes, immunotherapy-associated genes, and the genes expressed in tumor cells, we obtained a special biomarker CTNND1." (PMID 38169514, 2024). "CTNND1 was previously identified to bind and stabilize cadherins, further regulating Wnt/β-catenin signaling pathway activity during tumor progression, and the CTNND1 mutation was associated with adverse OS in the EA cohort." (PMID 35488336, 2022). "On the other hand, the existence of an isoform-specific antibody for CTNND1 pro-invasive splice variants turns this splicing candidate as a valuable new target to reduce tumour metastasis." (PMID 33845831, 2021). "Apart from that, our data verified that KCNQ1OT1 deficiency could suppress CRC tumor growth partly through the miR-329-3p/CTNND1 pathway in vivo." (PMID 32760218, 2020). "Consequently, loss of E-cadherin function or expression during tumor progression as a consequence of the epithelial to mesenchymal transition results in the translocation of CTNND1 from cell membrane to the cytoplasm and/or the nucleus." (PMID 29228664, 2017). "However, loss of E-cadherin during tumor progression leads to the cytoplasmic and nuclear translocation of CTNND1." (PMID 29228664, 2017). "Increasing evidence supports the association of CTNND1 with tumor development and progression." (PMID 27193094, 2016). "It was shown that overexpression and phosphorylation of CTNND1 in the cytoplasm could promote cadherin-deficient tumor metastasis by regulating the activity of the small GTPase." (PMID 19835603, 2009). "The expression of most proteins tended to increase from the primary tumor to the corresponding metastasis, except for cellular CTNND1 and both cellular and stromal ADAM10." (PMID 40075679, 2025). "Results showed that the CTNND1+ tumor cells presented significantly more interactions than CTNND1- tumor cells." (PMID 38169514, 2024). "The results showed that the expression of CTNND1 was significantly positively correlated with the tumor purity, and significantly negatively with tumor purity." (PMID 38169514, 2024). "Totally, compared with CTNND1- tumor cells, CTNND1+ tumor cells interacted with microenvironment subpopulations frequently, suggesting that the complex crosstalk between CTNND1+ tumor cells and other subpopulations will contribute to the formation of TME." (PMID 38169514, 2024). "Meanwhile, after binarizing the cells into CTNND1+ and CTNND1- groups, the rate of CTNND1+ cells were significantly higher in the tumor cells than in non-tumor cells, further supporting the viewpoint that CTNND1 was the biomarker of tumor cells." (PMID 38169514, 2024). "The CTNND1 gene was validated in single cell atlas, and the results showed that its expression in tumor cells was significantly higher than that in non-tumor cells." (PMID 38169514, 2024). "The two gene sets were intersected with anoikis related genes to obtain CTNND1, which was identified as an immune regulation related anoikis tumor marker." (PMID 38169514, 2024). "The study found that CTNND1 can be considered as a regulating upstream gene, targeting which is expected to activate the patient's immune system coincident with tumor cell killing." (PMID 38169514, 2024). "The CTNND1+ tumor cells showed more frequently crosstalk with other subpopulations, especially the immune subsets." (PMID 38169514, 2024). "Results showed that CTNND1+ tumor cells communicated with myeloid cells via ANXA1-FPR1/3, SIRPA-CD47, and LGALS9-CD44, which have been reported to involve in the inhibition of anti-tumor response 45-47." (PMID 38169514, 2024). "We found that CTNND1 was highly expressed in tumor tissues compared with para-tumor tissues and CTNND1 was specifically expressed in NSCLC." (PMID 38169514, 2024).
tumor (continued). "The results showed that the rate of CTNND1+ cells was significantly higher in the tumor cells than in non-tumor cells." (PMID 38169514, 2024). "The number of interactions among different subpopulations was compared between CTNND1+ and CTNND1- tumor cells." (PMID 38169514, 2024). "The PRD domain of MORC2 interacts with a cadherin-associated protein, catenin delta 1 (CTNND1), to promote tumor invasion and metastasis." (PMID 37892209, 2023). "By sponging miR-298, hsa_circ_0005797 modulated CTNND1 expression, and regulated EC cells proliferation, invasion in vitro, and tumor growth in vivo." (PMID 34852711, 2022). "Mechanistically, knockdown of CTNND1 promoted tumor cells EMT and homing to the bone via upregulation PI3K/AKT/HIF-1α/CXCR4 pathway." (PMID 34830862, 2021). "In vitro, we demonstrated that knockdown of CTNND1 accelerated epithelial–mesenchymal transformation (EMT) of tumor cells and their recruitment to bones." (PMID 34830862, 2021). "We further demonstrated that knockdown of CTNND1 not only enhanced intrinsic metastatic functions including migration and invasion, but also facilitated tumor recruitment to bones, an event through the CXCR4/CXCL12 axis by activating PI3K/AKT/HIF-1α pathway." (PMID 34830862, 2021). "In vivo experiments revealed that knockdown of CTNND1 enhanced tumor cells metastasis to bones and also increased neutrophils infiltration in bones." (PMID 34830862, 2021). "In recent years, researchers had discovered that the dysregulation of CTNND1 impaired the homeostasis in vivo, especially in tumor." (PMID 34830862, 2021). "To verify the activation of the PI3K/AKT pathway in vivo experiments, we examined its activation via IHC staining in the bone of mice bearing tumor with CTNND1 knockdown." (PMID 34830862, 2021). "That is to say, these findings implied that KCNQ1OT1deletion suppressed CRC tumor growth partly by regulating miR-329-3p/CTNND1 axis in vivo." (PMID 32760218, 2020). "In view of this finding, the levels of CTNND1 were assessed in human BCa samples and adjacent non-tumor tissues." (PMID 31913290, 2020). "Previously study reported that CTNND1 was a tumor-driver gene, whose alternative splicing was related to cell invasion and metastasis." (PMID 32273884, 2020). "Relative expression of PRKCA, FOXC2, and CTNND1 in all tumor samples, using the AgilentG4502A_07_3 array platform, were computed and visualized by a heat map." (PMID 29216867, 2017). "In the cytoplasm, CTNND1 promotes cell migration and, consequently, tumor invasion and metastasis through activation of Rho-family GTPases Rac1 and Cdc42 and inhibition of RhoA activity." (PMID 29228664, 2017). "It has been shown that β-catenin can regulate WNT11, Cyclin D1, and MMP7 in many tumor cells, and so we next examined the role of CTNND1-mediated modulation of these genes." (PMID 27193094, 2016). "As expected, silencing of CTNND1 in the typically aggressive SK-Hep-1 cells led to a dramatic decrease in tumor volume and weight." (PMID 27193094, 2016). "Significant correlations were found between CTNND1 expression and tumor diameter, microvascular invasion, and tumor differentiation." (PMID 27193094, 2016). "The central position of CRK in signaling cascades makes it likely that CRK affects several downstream targets, other than the p120-catenin (CTNND1) promoter, thereby promoting tumor progression, invasion and metastasis." (PMID 22848689, 2012). "Besides, our results also showed that some interactions associated with tumor stemness, chemoresistance, and angiogenesis, such as WNT7B-FZD4 and NOTHC1-JAG1 52, 53, were detected between CTNND1+ tumor cells and stromal cells." (PMID 38169514, 2024). "Notably, we calculated the difference in interaction numbers among various CTNND1+/- tumor cells and microenvironment subpopulations." (PMID 38169514, 2024).